TRAK1 (trafficking kinesin protein 1)
Description:
Involved in the regulation of endosome-to-lysosome trafficking, including endocytic trafficking of EGF-EGFR complexes and GABA-A receptors. Involved in mitochondrial motility. When O-glycosylated, abolishes mitochondrial motility. Crucial for recruiting OGT to the mitochondrial surface of neuronal processes. TRAK1 and RHOT form an essential protein complex that links KIF5 to mitochondria for light chain-independent, anterograde transport of mitochondria (By similarity).
Synonyms: KIAA1042; OIP106; MILT1; DEE68; EIEE68
Tractability: PROTAC: ubiquitination databases record sites on it.
Gene: Protein-coding gene on chromosome 3 (42,013,624 to 42,225,890, forward strand). Ensembl gene ENSG00000182606.
Subcellular location: Cytoplasm; Nucleus; Mitochondrion; Early endosome; Endosome; Mitochondrion membrane; Cytoplasm, cell cortex
Subcellular location (Human Protein Atlas): Endoplasmic reticulum; Nucleoplasm
Pathways (Reactome):
Signal Transduction: RHOT1 GTPase cycle; RHOT2 GTPase cycle
Disease: Signaling by BRAF and RAF1 fusions
Gene Ontology:
Molecular function: protein binding; GABA receptor binding; myosin binding; TPR domain binding
Biological process: endosome to lysosome transport; mitochondrion distribution; neurogenesis; protein O-linked glycosylation; protein targeting; regulation of transcription by RNA polymerase II; vesicle transport along microtubule; axonal transport of mitochondrion; dendrite morphogenesis; positive regulation of axonogenesis
Cellular component: cytoplasm; early endosome; endosome; mitochondrial membrane; mitochondrion; nucleus; cytoplasmic vesicle; cytosol; dendrite; axon cytoplasm; axonal growth cone; cell cortex; perinuclear region of cytoplasm
Genetic constraint (gnomAD): Loss-of-function variants: 28 observed, 83.25 expected, observed/expected ratio (o/e) 0.34, 90% interval 0.25 to 0.46. The upper end of that interval is the gene's LOEUF score, 0.46, which puts it in group 2 of 6, group 1 being the genes least tolerant of losing a copy. Missense variants: 1,000 observed, 1,171.9 expected, observed/expected ratio (o/e) 0.85, 90% interval 0.81 to 0.9. Synonymous variants: 463 observed, 480.67 expected, observed/expected ratio (o/e) 0.96, 90% interval 0.89 to 1.04.
Homologues: Orthologues: chimpanzee TRAK1 (99% identical), macaque TRAK1 (99% identical), dog TRAK1 (95% identical), pig TRAK1 (95% identical), mouse Trak1 (92% identical), rat Trak1 (92% identical), guinea pig TRAK1 (88% identical), tropical clawed frog trak1 (81% identical), rabbit TRAK1 (70% identical), zebrafish trak1a (59% identical), Drosophila melanogaster milt (31% identical), Caenorhabditis elegans trak-1 (16% identical). Paralogues in human: TRAK2 (44% identical), HAP1 (15% identical).